AGO2 (argonaute RISC catalytic component 2)
Diseases named in the same sentence as AGO2 in open-access papers (continued):
Sharing a sentence is not in itself a finding about the gene and the disease.
glioma (continued). "Interestingly, several of these L2b-targets, which are not bound by AGO2 in glioblastoma, are implicated in glioma, such as PCDH9 and AQP4 and show similar non-canonical target sites as we found in other L2-miRNA targets." (PMID 30865625, 2019). "Moreover, increased levels of Ago2 conveyed very poor prognosis in glioma." (PMID 29179434, 2017). "Of note, nuclear Ago2 was observed in glioma cells and both SART3 and PRPF8 were pulled-down by the Ago2 immunoprecipitation." (PMID 35033060, 2022). "Results showed that IGF2BP3 loss led to the notable reduction of ZNRF3 level enriched by Ago2 antibody in U251 cells, suggesting that IGF2BP3 knockdown weakened the interaction of ZNRF3 and RISC in glioma cells." (PMID 34657141, 2021). "RIP analysis revealed LINC00662, and miR-107 co-immunoprecipitate in Ago2 complex, and RT-qPCR analysis revealed that depletion of LINC00662 enhances miR-107 levels in glioma cells." (PMID 32913464, 2020). "The results suggested that miR-542-5p inhibitor transfection with pristimerin treatment enhance expression of AGO2 and decrease expression of PTPN1 significantly, which mean that pristimerin and miR-542-5p silence had the synergistic effect in glioma cells." (PMID 31015365, 2019). "Using an anti-AGO2 antibody, RNA immunoprecipitation (RIP) assays were performed to determine whether cNDC80 functions as a miRNA sponge in glioma cells." (PMID 36635757, 2023). "Here, we show that LINC00662 directly interacts with miR-107 in the Ago2 complex and presented negative correlation in glioma tissues." (PMID 32913464, 2020). "Results indicated that post-treatment with pristimerin and miR-542-5p silence had profoundly the same effect, elevated AGO2 and decreased PTPN1, which might be related with cell proliferation, lead to glioma progression." (PMID 31015365, 2019). "Besides, RIP assay results disclosed that SNHG10 exhibited strong enrichment in Ago2 group relative to IgG group, implying that SNHG10 might function as a ceRNA in glioma." (PMID 33298070, 2020). "Importantly, RIP analysis indicated that both miR‐1 and miR‐203a levels were enriched in RNA pulled down by ago2 in glioma cells transfected with Luc‐UCA1‐wt, but not in cells with Luc‐UCA1‐mut‐1 or Luc‐UCA1‐mut‐203a transfection." (PMID 30410864, 2018). "Furthermore, Ago2 protein upregulation is a very negative glioma prognostic factor." (PMID 29179434, 2017). "In A172 glioma cells the RIP assay results revealed that circPRKCI and miR-545 were both efficiently pulled down by the anti-Ago2 antibody, but not by the non-specific anti-IgG antibody." (PMID 31409777, 2019).
hepatocellular carcinoma (22 papers, 2012 to 2025). A malignant tumor that arises from hepatocytes. "AGO2 has also been linked to enhanced metastasis activity in hepatocellular carcinoma." (PMID 33668654, 2021). "Overexpression of AGO2 was associated with high-risk myeloma and invasive hepatocellular carcinoma (HCC), while AGO2 knockdown caused a decline in viability and transferability of myeloma cell lines and HCC respectively." (PMID 28903378, 2017). "Ago2 administration normalizes endothelial cells in the mouse cortex and exerts angiogenic effects in human hepatocellular carcinoma through VEGF signaling." (PMID 36769259, 2023). "Overexpression of Ago2 promotes proliferation in hepatocellular carcinoma, while Ago2 knock-down induces apoptosis in myeloid leukemia cells." (PMID 36769259, 2023). "Argonaute2 (AGO2) promotes FAK expression by binding to the FAK promoter in a micro-RNA biosynthesis-independent manner in hepatocellular carcinoma (HCC)." (PMID 35163650, 2022). "The expression of AGO2 in six hepatocellular carcinoma cell lines was correlated with the expression and release of VEGF, a key factor promoting vascularization." (PMID 33668654, 2021). "Depletion of cellular Ago2 in human hepatoma cells reduces HCV RNA levels suggesting that miR-122 binds to an Ago2 containing complex to exert its effect." (PMID 23202492, 2012). "Furthermore, since AGO2 has been reported to stabilize c-Myc to facilitate stem cell renewal and differentiation, leading to tumorigenesis and progression of hepatocellular carcinomas." (PMID 36613808, 2022). "Moreover, there was a notable reduction in hepatocellular carcinoma tumorigenicity upon miR-99a overexpression or AGO2 silencing, which points to an oncogenic potential of AGO2." (PMID 33668654, 2021). "The production of AGO2 was found to be attenuated by miR-99a in hepatocellular carcinoma cells." (PMID 33668654, 2021). "Phosphorylation of Exportin-5 correlated with the global down-regulation of miRNAs and unfavorable prognosis of patients with hepatocellular carcinoma (HCC), while Ago2 protein was found to be up-regulated in various types of cancer." (PMID 35628648, 2022). "The AGO2 chromosomal position, 8q24.3, constitutes a frequently amplified locus in many cancer types, including the Hepatocellular Carcinoma (HCC)." (PMID 32503341, 2020). "In hepatocellular carcinoma, PABPC1 interacts with AGO2 to augment miRNA repression by facilitating RISC binding and enhancing miRNA-mediated deadenylation, leading to the inhibition of tumor suppressor genes." (PMID 35346324, 2022). "Additionally, AGO2 was found to tether MYC mRNA, increasing its stability in hepatocellular cancer cells, and therefore promote cell survival and proliferation." (PMID 33668654, 2021). "In this study, we found that AGO2 expression was remarkably increased in human hepatocellular carcinoma (HCC) tissues when compared with adjacent noncancerous tissues." (PMID 32420319, 2020). "However, in line with later studies, we did not observe TRIM71-mediated changes in AGO2 stability in the cell lines tested, including the hepatocellular carcinoma line HepG2." (PMID 31732746, 2019).
prostate carcinoma (21 papers, 2010 to 2025). A carcinoma that arises from epithelial cells of the prostate gland. "Documented evidence showed that higher expression of AGO2 was directly associated with prostate cancer cell proliferation, apoptosis, and cell cycle regulation." (PMID 31756185, 2019). "Indeed, down-regulation of AGO2 has been associated with cell proliferation and apoptosis in prostate cancer." (PMID 40698645, 2025). "Elevated Dicer and Ago2 expression in prostate cancer tissues compared to adjacent benign tissues have been linked to lower Gleason scores, suggesting a role in moderating tumor aggression." (PMID 40034825, 2025). "When Dicer or Ago2 expression is silenced in vitro, prostate cancer cell lines such as LNCaP, PC-3, and DU145 exhibit significant reductions in cell proliferation and increased cell death, indicating Dicer’s role in promoting tumor cell survival." (PMID 40034825, 2025). "The assay demonstrated significant enrichment of both circ_0001671 and miR-27b-3p in the anti-Ago2 group compared to the anti-IgG group, suggesting a regulatory role for circ_0001671 in prostate cancer." (PMID 38806577, 2024). "We found that circROBO1, miR-556-5p, and PGK1 mRNA were all enriched to RNA induced silencing complex in both C4-2B and 22RV1 prostate cancer cells, assessed by the anti-Ago2 related RIP assays." (PMID 37670963, 2023). "Downregulation of miR-100 promoted prostate cancer metastasis by upregulating Argonaute 2 (AGO2), a core effector protein of the miRNA-induced silencing complex which facilitates EMT." (PMID 27588490, 2016). "Recently it has been demonstrated that AGO2 was a direct target of miR-100 which is involved in regulation of bone metastatic process in prostate cancer." (PMID 25019555, 2014). "Indeed, this is supported by previous work that found silencing of Ago2 resulted in a G2/M arrest in prostate cancer cells." (PMID 31324173, 2019). "The upstream regulators identified in advanced-stage prostate cancer in both PC3 and DU145 cells includes (i) AGO2, (ii) SSB, and (iii) neurofibromatosis 2 (NF2), and (iv) DICER1." (PMID 31756185, 2019). "In particular downregulation of AGO2 by miR-100 repressed migration, invasion, EMT and stemness of prostate cancer cells." (PMID 25019555, 2014). "In the present study the expression of AGO2, SSB, and NF2 is downregulated in early-stage cancer and upregulated in advance-stage cancer; whereas PPARA was overexpressed and DICER1 was inhibited across all stages of prostate cancer." (PMID 31756185, 2019). "EIF2C2 (AGO2) transcript presents contrasting regulation depending on the cell line whereas EIF2C4 (AGO4) appears to be up-regulated in two other cell lines (HUVEC and prostate cancer at 48 h and 72 h of hypoxia, respectively." (PMID 24517586, 2014). "We apply our theoretical predictions of diffusion times and lower limits for the time resolution of two components to fluorescence images in human prostate cancer cells (PC-3) transfected with fusion proteins of green fluorescence protein (GFP) and argonaute proteins (Ago1, Ago2)." (PMID 20553227, 2010). "circSPIRE1 exhibited only weak binding affinity with Argonaute 2 (AGO2), indicating that circSPIRE1 is unlikely to exert its biological effects in prostate cancer through the miRNA sponge mechanism." (PMID 40713830, 2025). "It has been reported that the absence of miR-100-5p leads to the upregulation of AGO2 expression levels, thus promoting the migration, invasion and EMT of cancer cells and promoting the metastasis of prostate cancer." (PMID 33335853, 2020).
lung carcinoma (20 papers, 2017 to 2026). "Compared with noncancerous lung tissues, the levels of plasma membrane-associated Ago2 were significantly higher in lung carcinomas (P = 1.37 × 10−4; Fig. EV4C)." (PMID 38649663, 2024). "By employing public clinical data, the Kaplan–Meier survival analysis revealed that lung cancer patients with the high levels of AGO2 had a lower survival rate than those with the low levels of AGO2, suggesting that the high expression levels of AGO2 may be a risk factor of lung cancer." (PMID 30305728, 2019). "The exosomes showed significantly higher levels of miR‐93‐5p compared to very low levels in the Ago2 IPs from the same lung cancer patients." (PMID 41159542, 2026). "The P300/CBP/AGO2/miR-19b axis promotes growth and proliferation of A549, a lung cancer cell line, and in vivo lung cancer xenograft mouse model." (PMID 33668654, 2021). "In fact, overexpression of AGO2 resulted in decreased proliferation and motility of H1299 lung cancer cells." (PMID 33668654, 2021). "CircRNF13 is capable of reducing the proliferation and viability of lung cancer cells by down-regulation of miR-93-5p through interacting with Ago2." (PMID 32612456, 2020). "By analyses on public clinical data, xenograft mouse models, and IHC and ISH staining of lung cancer tissue arrays, we confirm that AGO2 acetylation promotes cancer progression by increasing miR-19b maturation." (PMID 30305728, 2019). "Analyses on public clinical data, xenograft mouse models, and IHC and ISH staining of lung cancer tissues, further confirm that the high levels of both AGO2 acetylation and miR-19b correlate with poor prognosis in lung cancer patients." (PMID 30305728, 2019). "Here, we further investigated the interaction between MALAT1 and miR-101, miR-101 and SOX9 in lung cancer cells using RNA immunoprecipitation assays with the AGO2 antibody." (PMID 29212230, 2017). "Similarly, AGO2-CAV-1 interaction augments miR-3613-3p-mediated suppression of SCAI mRNAs in A549 lung cancer cells." (PMID 40863728, 2025). "Finally, the investigators revealed that the elevated acetylation of AGO2 promotes the biogenesis of oncogenic miR-19b and leads to an aggressive type of lung cancer, as observed in Xenograft mouse models." (PMID 40863728, 2025). "Similarly, other research has demonstrated that hnRNP I can facilitate the association of AGO2 with MCL1 mRNA via the miR-101-loaded miRISC, thus inhibiting the expression of MCL1 and suppressing its antiapoptotic and prosurvival effects on lung cancer cells." (PMID 38689093, 2024). "The results suggest that the association of Ago2 with endosomes increases in A549 lung cancer cells but CBM of Ago2 is not required for the increased association of Ago2 and endosomes in the cancer cells." (PMID 38649663, 2024). "The results suggest that the association of Ago2 and ER remains the same in both normal lung epithelial cells and lung cancer cells and deletion of CBM of Ago2 does not affect the association of Ago2 with ER in cancer cells." (PMID 38649663, 2024). "We also analyzed the distribution of Ago2 in lung tissues and lung carcinomas (Fig. EV4C)." (PMID 38649663, 2024). "According to these pathways, AGO2 may act as a tumor suppressor in lung cancer patients, which contradicted its high amplification rate in our results." (PMID 36761423, 2022). "In this study, an RNA binding protein immunoprecipitation (RIP) experiment was performed in lung-cancer-resistant cell extracts using an antibody against Ago2 to determine whether CK2α and miR-499 belong to the same RISC." (PMID 33997273, 2021). "Due to the Ago2 protein, this circRNA is capable of sponging the miR-93 that in turn, enhances the expression of leukemia inhibitory factor receptor, as a tumor suppressor leading to the reduced metastasis and viability of lung cancer cells." (PMID 32612456, 2020).
lung carcinoma (continued). "Accordingly, PABPC1 is an RNA-binding member of the eIF4F complex responsible for the circularization of the mRNA before binding of the ribosomal subunits and has been found upregulated in lung cancer and in interaction with AGO2, which plays a key role in miRNA-mediated gene silencing." (PMID 33092114, 2020). "In the present study, we determined that LCAT1 is mainly localized to the cytoplasm and interacts with Ago2 in lung cancer cells, suggesting that LCAT1 may function as an endogenous miRNA sponge." (PMID 31779616, 2019). "Taken together, above findings demonstrate that the high acetylation levels of AGO2 at K493 and K720 are positively correlated with miR-19b expression in lung cancers, revealing a novel mechanism that AGO2 acetylation promotes tumorigenesis by enhancing miR-19b maturation." (PMID 30305728, 2019). "Thus, our results provide crucial insight into how miR-19b maturation is regulated by AGO2 acetylation and why miR-19b is highly expressed in lung cancer." (PMID 30305728, 2019). "It is notable that AGO2 could directly interact with P300 to promote lung cancer progression." (PMID 38585233, 2024). "Our results show that miR‐93‐5p is predominantly found in RBC‐derived exosomes, not in the Ago2 complex, indicating that exosomes serve as the primary vehicle for delivering this oncogenic miRNA from RBCs to lung cancer cells." (PMID 41159542, 2026). "Immunofluorescence analysis showed that Ago2 was distributed throughout the nuclei and cytoplasm in normal epithelial cells (i.e., BEAS-2B human lung epithelial cells) and was mainly distributed in cytoplasm and membrane of cancer cells (i.e., A549 lung cancer cells)." (PMID 38649663, 2024). "In addition, the phosphorylation of argonaute 2 (AGO2) by c-Src inhibits the binding of DICER to AGO2 and promotes tumorigenesis of lung cancer, suggesting that change of these miRNA biogenesis related genes might cause alternation of miRNA signature in NSCLC." (PMID 33898432, 2021).
melanoma (19 papers, 2014 to 2025). A malignant, usually aggressive tumor composed of atypical, neoplastic melanocytes. "Expression of AGO2-ex1/3 provides a survival advantage for melanoma cells while the knockdown causes significantly reduced proliferation and increases apoptosis." (PMID 35943635, 2022). "This makes this newly identified AGO2 splice variant an interesting target gene in melanoma and an important molecule considering small RNA-based therapies." (PMID 35943635, 2022). "This study identified a new splice variant of the miRNA-binding protein AGO2 in melanoma cells, missing exon 2 in the CDS." (PMID 35943635, 2022). "Flow cytometry analysis revealed that ectopic expression of Ago2 decreases the cell-surface level of MHC I and infiltration and cytotoxicity of CD8+ T cells in Mll4−/− melanomas, which probably underlie the rescuing effects of exogenous Ago2 expression on Mll4−/− melanoma progression in vivo." (PMID 36323669, 2022). "The data revealed in this study indicate a growth advantage of melanoma cells expressing a previously unknown AGO2 variant and a potential functional significance of this variant for the miRNA pathway." (PMID 35943635, 2022). "Focusing on AGO2 in melanoma cells, we identified a new splice variant of AGO2." (PMID 35943635, 2022). "AGO2-RIP-qRT‒PCR assays demonstrated that the NF2 and CISD3 mRNAs were markedly enriched in the AGO2-miR-150-3p complex, a finding corroborated by their upregulation in miR-150-3p knockout melanoma cells." (PMID 40860143, 2025). "Biochemical fractionation revealed that siRNA-mediated reduction of either Lamin A/C or Lamin B1 levels triggered AGO2 nuclear translocation in both A375 melanoma and SHSY5Y neuroblastoma cells." (PMID 38994560, 2024). "To find out, if the N-terminally truncated AGO2 protein version is also endogenously translated from the AGO2-ex1/3 mRNA in melanoma cells, we used an antibody targeting a C-terminal region of the AGO2 protein." (PMID 35943635, 2022). "To analyze the effect on growth in melanoma cells after AGO2-ex1/3 knockdown in more detail, we measured cell viability using an XTT-assay." (PMID 35943635, 2022). "Transfection of the melanoma cell lines Mel Im and Mel Juso with siAGO2-ex1/3 leads to a reduction of AGO2-ex1/3 mRNA expression of about 34–45% after 24 h." (PMID 35943635, 2022). "After transfection of this construct into the melanoma cell lines Mel Im and Mel Juso, the AGO2-ex1/3-GFP fusion protein should be detected in the Western blot at a size of about 33 kDa." (PMID 35943635, 2022). "To understand the molecular mechanisms affected by knockdown of AGO2-ex1/3, which induce the observed reduction in proliferation and increase in apoptosis, we performed RNA-Seq after siAGO2-ex1/3 transfection in the melanoma cell line Mel Juso." (PMID 35943635, 2022). "To be able to analyze endogenous AGO2-ex1/3 protein expression in melanoma cells, we performed a genetic knockout of full-length AGO2 in the melanoma cell lines Mel Im and Mel Juso using CRISPR/Cas9." (PMID 35943635, 2022). "To identify such miRNAs, we analyzed a connection of miRNAs which are highly expressed in melanoma cell lines compared to NHEM with a deregulation of microRNA target genes after AGO2-ex1/3 knockdown." (PMID 35943635, 2022). "Quantitative real-time PCR revealed expression of AGO2-ex1/3 in several different melanoma cell lines and an elevated expression in some cell lines compared to healthy melanocytes." (PMID 35943635, 2022). "Due to a defect in miRNA regulation, numerous target genes involved in various cellular processes are aberrantly expressed, which ultimately leads to the observed apoptosis after AGO2-ex1/3 knockdown in melanoma cells." (PMID 35943635, 2022). "One possible explanation for the reduced cell growth of melanoma cells after downregulation of AGO2-ex1/3 would be the occurrence of a cell cycle arrest, e.g., by induction of senescence." (PMID 35943635, 2022).